HTT (huntingtin)
Diseases named in the same sentence as HTT in open-access papers (continued):
Sharing a sentence is not in itself a finding about the gene and the disease.
Huntington disease (continued). "Huntington’s disease has also been shown to display defective degradation of mitochondria and polyglutamine-expanded Huntingtin aggregates (Huntingtin is a protein with no homology to other proteins, highly expressed in neurons." (PMID 36831186, 2023). "Huntington’s disease (HD) presents a genetic neurodegenerative disorder that is inherited in an autosomal dominant manner, attributed to CAG and, subsequently, polyglutamine (polyQ) repeat expansions in the Huntingtin gene (HTT) and protein, respectively." (PMID 37759656, 2023). "In people with Huntington’s disease, the expression of mutant Huntingtin does not have the same impact on the various types of neurons across the brain." (PMID 37020532, 2023). "PAK1-mediated oligomerization of Huntingtin (HTT), which is independent of PAK1 kinase activity, is associated with Huntington’s disease." (PMID 36937657, 2023). "Moreover, TUDCA ameliorates striatal apoptosis, cerebral and striatal atrophy, and sensorimotor deficits in R6/2 transgenic mice that carry the human huntingtin gene which has 144 CAG repeats and are commonly used as a model for Huntington’s disease." (PMID 37107583, 2023). "Huntington's disease (HD) is a neurodegenerative disorder with a variable-length expansion of the CAG (Cytosine, Adenine, Guanine) trinucleotide repeat in exon 1 of the Huntingtin (HTT) gene." (PMID 37153428, 2023). "Another example is Huntington’s Disease (HD), a neurodegenerative disease in which the age-of-onset of symptoms has a positive correlation with the number of CAG repeats in the first exon of the Huntingtin gene." (PMID 36699015, 2022). "Huntington’s disease (HD) is an autosomal-dominant inheritable neurodegenerative disorder that results from a CAG repeat extension in exon 1 of the huntingtin gene (HTT), which translates into a long polyQ repeat in the huntingtin protein." (PMID 36311026, 2022). "In contrast, for Huntington’s disease (HTT gene), also resulting from a non-haploinsufficiency disease mechanism, the use of gapmer AONs to target a SNP specific to the mutant allele emerged as a promising therapeutic strategy in vitro and in vivo." (PMID 33815940, 2021). "Das found that heat stress induces Huntington’s disease in mice, and HYPK (Huntingtin Yeast Partner K) could alleviate huntington’s reaction by suppressing the heat shock response." (PMID 32787853, 2020). "Having previously shown that Huntingtin (HTT), the scaffolding protein involved in Huntington’s disease, regulates neuritic transport of APP, we used a microfluidic corticocortical neuronal network-on-a-chip to examine APP transport and localization to the pre- and post-synaptic compartments." (PMID 32452382, 2020). "In addition, huntingtin (HTT) protein containing pathologic polyQ expansions aggregates near the nucleus and disrupts the envelope, while the transgenic R6/2 mouse model of Huntington’s disease displays severe alterations of lamina structure." (PMID 32630170, 2020). "We and others have shown that wild-type huntingtin (HTT), but not the polyglutamine-expanded HTT that causes Huntington’s disease (HD), facilitates APP transport by increasing the velocity of APP-containing vesicles." (PMID 32452382, 2020). "Huntington’s disease is an autosomal dominant neurodegenerative disorder that results from the expansion of a CAG repeat in the huntingtin gene (HTT), which is translated to polyglutamine (polyQ) in the huntingtin protein (HTT)." (PMID 31075835, 2019). "Despite the well-known function of the HTT gene in Huntington’s disease, SNPs within the identified locus near this gene have not been associated with the disease at genome-wide significance." (PMID 30642433, 2019). "In Huntington disease (HD), Sirt1 is not able to deacetylate TORC1 that in consequence does not bind CREB, due to the presence of mutated huntingtin protein interfering with TORC1-CREB complex." (PMID 30304806, 2018).
Huntington disease (continued). "The level of this read-through product is proportional to CAG repeat length and is present in all knock-in mouse models of Huntington’s disease (HD) with CAG lengths of 50 and above and in the YAC128 and BACHD mouse models, both of which express a copy of the human HTT gene." (PMID 28465506, 2017). "Unlike HIP1, HIP1R protein does not interact with the huntingtin protein directly and there is no obvious evidence for its involvement in Huntington’s disease (HD)." (PMID 28663723, 2017). "Huntington’s disease (HD) is an autosomal dominant movement disorder, typically characterized by chorea, cognitive decline, and behavioral changes, due to a trinucleotide (CAG) repeat expansion in the HTT gene." (PMID 28789621, 2017). "In a model of Huntington's disease, oxidation of methionine residues in the abnormal huntingtin protein occurs only in the aggregated protein, but not in the soluble state." (PMID 26333167, 2015). "Despite 20 years since its discovery, the gene responsible for Huntington’s Disease, HTT, has still not had its function or transcriptional profile completely characterized." (PMID 26496077, 2015). "We have focused on n = 60 which, if present in huntingtin protein, would result in Huntington disease, and on n = 20, which would not." (PMID 26495838, 2015). "Neuronally differentiated iPS cells derived from transgenic animals expressing huntingtin exon-1 with expanded polyQ form inclusions, whereas fibroblasts of patients with Huntington disease do not form microscopic aggregates." (PMID 24961702, 2014). "Although these fragments must be generated in both affected and unaffected brain regions, water-soluble N-terminal fragments of expanded huntingtin are found in Huntington disease cortex but not in the cerebellum." (PMID 24961702, 2014). "The PD-increased hsa-miR-21 (log fold change: 1.3, p-value: 0.02) also participates in a miRNA-based gene dys-regulation pathway in Huntington's disease, and potentiated suppression by hsa-miR-21 and hsa-miR-150 of PTEN and Huntingtin would intercept T- and B- cells proliferation." (PMID 23717260, 2013). "Huntington disease (HD) is frequently first diagnosed by the appearance of motor symptoms; the diagnosis is subsequently confirmed by the presence of expanded CAG repeats (> 35) in the HUNTINGTIN (HTT) gene." (PMID 23874679, 2013). "Huntington disease (HD) is one of the neurodegenerative disorders where the origin has been unequivocally identified, that is, an elongation of polyglutamine (>35 CAG repeats) in the HUNTINGTIN (HTT) gene on chromosome 4." (PMID 24223692, 2013). "Huntington’s disease (HD) is an autosomal dominant genetic disorder, resulting from expansion of a stretch of CAG repeats near the N-terminus of the Htt HD gene on chromosome 4, coding for the protein huntingtin." (PMID 23925262, 2012). "In Huntington's disease patients, the CAG repeats of the huntingtin gene expand in an age-dependent manner in brain tissues, especially the striatum, leading to the formation of huntingtin protein aggregates in the cytoplasm." (PMID 22028931, 2011). "Huntington’s disease (HD) is an inherited neurodegenerative disease, caused by a CAG tripletrepeat expansion in the gene encoding huntingtin, for which there is no effectivedisease-slowing treatment." (PMID 21826115, 2011). "Indeed, in SOD1-related ALS, Huntington's disease, and Alzheimer's disease, specific neuronal subtypes are affected despite ubiquitous expression of SOD1, huntingtin and APP, respectively." (PMID 19266020, 2009). "We identified and annotated 14 candidate Huntington’s disease modifier genes independent of HTT interrupting sequence signals that may play a role in modifying the AOO in Huntington’s disease." (PMID 39801710, 2025).
Huntington disease (continued). "Huntington’s disease (HD) is a fatal, heritable neurodegenerative disorder characterized by the pathological expansion of the CAG trinucleotide repeat in the Huntingtin (HTT) gene, resulting in an aberrant polyglutamine (polyQ) tract within the mutant HTT protein (mHTT)." (PMID 41567979, 2025). "Multiple studies also focused on treating Huntington’s disease (HD), a neuro-degenerative disease that occurs as a result of an autosomal Deoxyribonucleic Acid (DNA) dominant inheritance pattern in the form of repeated CAG trinucleotide in the huntingtin “HTT” gene." (PMID 41304419, 2025). "Here, we report the generation and characterization of a novel Huntington’s disease (HD) mouse model BAC226Q by using a bacterial artificial chromosome (BAC) system, expressing full-length human HTT with ~226 CAG-CAA repeats and containing endogenous human HTT promoter and regulatory elements." (PMID 35023827, 2022). "Structural changes and neuropathology in the hypothalamus have been suggested to contribute to the non-motor manifestations of Huntington’s disease (HD), a neurodegenerative disorder caused by an expanded cytosine-adenine-guanine (CAG) repeat in the huntingtin (HTT) gene." (PMID 36408416, 2022). "In another interesting report, the length of uninterrupted CAG repeats in DNA, rather than the polyQ length at the N-terminal of HTT was found to be a critical contributing factor in HD disease onset (Genetic Modifiers of Huntington’s Disease [GeM-HD] Consortium, 2019)." (PMID 35444517, 2022). "An example case is a recent report on Huntington’s disease (HD), a monogenic, autosomal-dominant trinucleotide CAG-repeat expansion within exon 1 of the HTT gene, resulting in an abnormally long polyglutamine (polyQ) tract of the mutant Huntingtin (mHTT) protein." (PMID 31963584, 2020). "We conclude that SRSF6 is not required for the incomplete splicing of HTT in Huntington’s disease." (PMID 32820193, 2020). "In Huntington disease (HD), Ogg1 (and/or Neil1)-initiated repair of 8-oxoguanine (8-oxoG, or oxidized pyrimidines) in CAG triplets is proposed to trigger iterative oxidation–excision cycles that contribute to the somatic instability of the huntingtin gene, through a CAG repeat expansion." (PMID 32192183, 2020). "Huntington’s disease (HD), is an autosomal dominant inherited neurodegenerative disorder, resulting from an abnormal CAG-repeat expansion in the coding region of the HTT gene, resulting in an expanded polyglutamine (polyQ) tract of the huntingtin protein (HTT)." (PMID 32276655, 2020). "Huntington’s disease (HD) is an autosomal dominant, inherited neurodegenerative disease, which is mainly due to the excessive expansion of CAG trinucleotide repeats in the huntingtin gene in chromosome 4, leading to the abnormal of polyglutamine near the N-terminal of the HTT." (PMID 32158393, 2020). "Indeed, REST seems dysregulated in the striatal tissue of Huntington’s disease (HD) patients and HD mouse models, where nuclear availability of REST in striatal neurons is modulated through its interaction with the huntingtin protein." (PMID 31165472, 2019). "Huntingtin is essential for neuron survival, and the lack of huntingtin synthesis may lead to Huntington's disease." (PMID 30066726, 2018). "In contrast to the innate immune system, the intrinsic phenotype of T lymphocytes does not appear to be affected by the presence of mutant huntingtin, with Huntington’s disease T lymphocytes exhibiting no significant functional differences compared to control cells." (PMID 26529236, 2015). "Also, a specific increase in GluN2B-containing NMDARs in medium-sized spiny striatal neurons, specifically at extrasynaptic locations, contributes to phenotype onset in a model of Huntington's disease, where the synaptic/extrasynaptic NMDAR balance controls mutant Huntingtin toxicity." (PMID 22578505, 2012).
Huntington disease (continued). "We found that heterologous expression of huntingtin fragments 25Q and 103Q in yeast increased PEA level by ∼2 fold, showing that the ability of huntingtin to control PEA levels does not depend on the length of the polyglutamine repeat that determines the age of onset of Huntington's disease." (PMID 19529773, 2009). "Lithium chloride treatment reduced toxicity induced by overexpression of Huntington disease exon 1 fragment with 74 glutamines in neuronal and non-neuronal cell lines, and attenuated toxicity of the N-terminal part of mutant huntingtin with 120 glutamine repeats in Drosophila." (PMID 17535104, 2007). "Similarly, while a dose-dependent decrease in mutant HTT protein was observed in the CSF of patients with Huntington’s disease, there was no change in functional, neurological, psychiatric or cognitive outcomes in patients who received placebo versus those receiving active treatment." (PMID 37240368, 2023). "However, since these alterations do not parallel the temporal spread of mutant huntingtin aggregates, the R6/1 retina may be more useful for investigating Huntington’s disease mechanisms and therapeutic strategies rather than serving as an early diagnostic marker." (PMID 41294851, 2025). "The paucity of mechanistic information on IKK pathways, together with the lack of sensitive methods to quantify endogenous huntingtin phosphorylation, prevented detailed study of the role of IKBKB in Huntington’s disease." (PMID 37553253, 2023). "In addition, in Huntington disease, where the cerebellum is not a region primarily affected, the CAG repeat expansion on the Huntingtin gene is the most stable in the cerebellum." (PMID 38626762, 2024). "However, concerning Huntington’s disease, no reports of over-expression of C-ABL and its interaction with HTT protein in any of the HD mouse models to date." (PMID 33420088, 2021). "Because Huntingtin is not an established component of RNP granules, these observations support a recently hypothesized, unexpected protein-handling function for RNP granules, which could contribute to the progression of Huntington’s disease and, potentially, other proteinopathies." (PMID 34718534, 2021).
Parkinson disease (123 papers, 2005 to 2026). A progressive degenerative disorder of the central nervous system characterized by loss of dopamine producing neurons in the substantia nigra and the presence of Lewy bodies in the substantia nigra and locus coeruleus. "AD is marked by tau and amyloid plaque buildup, Parkinson’s disease by α-synuclein accumulation causing dopamine cell loss and Huntington’s disease by Huntingtin (Htt) aggregates." (PMID 41145616, 2025). "This study aimed to investigate the influence of CAG repeat sizes in ATXN1, ATXN2 and HTT genes on the risk for developing cancer and Parkinson’s disease in a large cohort of patients with idiopathic Parkinson’s disease and healthy controls." (PMID 39974178, 2025). "Such proteins, like mutant huntingtin (HD), α-synuclein (Parkinson’s disease) and tau (in various dementias), cause pathology via toxic gain-of-function mechanisms." (PMID 31000720, 2019). "Similar as mutant SOD1 (mSOD1), intraneuronal accumulation of misfolded Parkin and polyglutamine (polyQ)-expanded Huntingtin (Htt) proteins is associated with the neurodegenerative disorders Parkinson’s and Huntington’s disease, respectively." (PMID 24691167, 2014). "This machinery, composed of the constitutive Hsp70 (Hsc70), the class B J-protein DnaJB1 and the nucleotide exchange factor Apg2 (Hsp110), disassembles amyloids of α-synuclein implicated in Parkinson’s disease as well as of other disease-associated proteins such as tau and huntingtin." (PMID 34685723, 2021). "In Parkinson disease and HD, damaged mitochondria and causative proteins (alpha-synuclein and to a much smaller extent, tau in PD, and mutant huntingtin in HD) accumulate in affected neurons, indicating a problem with autophagy or the ubiquitin/proteasome system." (PMID 32210766, 2020). "Misfolding- and aggregation-prone proteins underlying Parkinson's, Huntington's and Machado-Joseph diseases, namely α-synuclein, huntingtin, and ataxin-3 respectively, adopt numerous intracellular conformations during pathogenesis, including globular intermediates and insoluble amyloid-like fibrils." (PMID 19492089, 2009). "In addition, the filaments derived from alpha‐synuclein, polyQ‐expanded huntingtin, and beta‐amyloid, which are associated with the neurodegenerative disorders such as Parkinson's, Huntington‘s, and Alzheimer's diseases, respectively, also trigger ER stress in neurons." (PMID 37646198, 2023). "Aggregation of the misfolded proteins β-amyloid, tau, huntingtin, and α-synuclein is one of the most important steps in the pathology underlying a wide spectrum of neurodegenerative disorders, including the two most common ones—Alzheimer’s and Parkinson’s disease." (PMID 32629809, 2020). "There is strong evidence that GAPDH can interact with β-amyloid and huntingtin proteins to regulate their cytotoxicity, thus directly linking to several neurodegenerative disorders, such as Alzheimer’s, Huntington’s, and Parkinson’s diseases." (PMID 36450447, 2023). "Many pathogenic proteins, which are thought to be responsible for neurodegenerative diseases, are Hsp90 clients or interactors, including tau (Alzheimer’s disease), α-synuclein (αSyn, Parkinson’s disease), and huntingtin (Htt, Huntington’s disease)." (PMID 34677645, 2021). "Protein aggregates are the hallmarks of several neurodegenerative disease, for example, amyloid beta and tau in Alzheimer’s disease, alpha-synuclein in Parkinson’s disease (PD), and huntingtin in Huntington’s disease." (PMID 32581709, 2020). "Antidepressants and other psychotropic medication are frequently prescribed to patients suffering from Alzheimer’s, Huntingtin’s, Parkinson’s and other neurodegenerative diseases." (PMID 30642024, 2019). "This has been demonstrated for huntingtin protein in Hungtington’s disease, alpha-synuclein in Parkinson’s disease, and amyloid beta in AD: however, evidence for this phenomenon in the case of tau aggregation is only beginning to emerge now." (PMID 23964266, 2013).